BRCA1 (BRCA1 DNA repair associated)
Diseases named in the same sentence as BRCA1 in open-access papers (continued):
Sharing a sentence is not in itself a finding about the gene and the disease.
tumor (continued). "Together, the results of this study support the hypothesis of a causative link between altered function of AURKA-HMMR-TPX2-TUBG1 and breast carcinogenesis in BRCA1/2 mutation carriers." (PMID 25830658, 2015). "This difference in CNAs profiles might be explained by the need for BRCA1-deficient tumor cells to acquire survival factors, by for example specific copy number aberrations, to expand." (PMID 26553136, 2015). "However, the role of these less expected processes in BRCA1/2-associated breast carcinogenesis needs to be further examined." (PMID 26378051, 2015). "Therefore, it seems likely that BRCA1-mutated cells acquire survival factors that allow BRCA1-deficient tumor cells to expand." (PMID 26553136, 2015). "Univariate analysis revealed that negative staining of ER (P = 0.007, odds ratio (OR) = 3.49), nNHERF1 (P = 0.039, OR = 4.41), HIF-1α (P = 0.032, OR = 2.78) and BRCA1 (P = 0.035, OR = 2.56) and positive cBRIT1 (P = 0.02, OR = 3.11) expression were significantly associated with large tumor size." (PMID 26312763, 2015). "These authors underlined the role of nuclear BRCA1 as a tumor suppressor in BC, and its underexpression might be correlated with a more invasive tumor phenotype." (PMID 26312763, 2015). "Moreover, we also observed that FOXA1 expression was significantly lower in BRCA1-mutated tumours compared with BRCA2, BRCAx and BRCA2/x tumours (P<0.001, P=0.001 and P<0.001, respectively; Student's t-test)." (PMID 25531315, 2015). "Besides the study of BRCA1 alleles in the tumor, different patterns characterizing BRCA1-driven tumors have been accessed." (PMID 26426992, 2015). "Even without excluding protein coding sequence mutants, we found BRCA1 expression was significantly lower in TNBC tumor cores from patients harboring the BRCA1-3’UTR-variant (TT) alleles compared to patients harboring hetero and homozygous wild-type (TG and GG) alleles." (PMID 24915755, 2014). "Triple-negative tumor status was highly predictive of BRCA1 mutation status for women younger than 50 years (LR = 3.73 (3.43 to 4.05)) and 50 years or older (LR = 4.41 (3.86 to 5.04)), and modestly predictive of positive BRCA2 mutation status in women 50 years or older (LR = 1.79 (1.42 to 2.24))." (PMID 25857409, 2014). "Given successful tumor growth inhibition by cisplatin and the cisplatin/olaparib combination in Brca1-deficient orthotopic models, we asked whether responses to long term treatment with olaparib would reflect these human outcomes." (PMID 24748377, 2014). "Both of these findings could help explain the association of the BRCA1-3’UTR-variant with tumor progression and aggressive phenotype." (PMID 24915755, 2014). "Importantly, it has been shown that depletion of AKT significantly reduces tumor formation induced by Brca1 deficiency in the KO mice." (PMID 25426449, 2014). "The influence of sex hormones on tubal/ovarian malignant transformation is not well understood, but seems likely that the BRCA1/2 associated changes in reproductive hormones and their receptors play a role in tumor formation, in addition to the alterations in DNA damage repair." (PMID 24478985, 2014). "Thus, it stands to reason that BRCA1 and its associated kinases sense oxidative stress and activate tumor suppression activities." (PMID 24704793, 2014). "An association among the expression of TILs, cytokines, and mutation of BRCA1 was also verified, suggesting that all of these factors may play a role in tumor progression." (PMID 24672781, 2014).
tumor (continued). "The suggested progression-promoting effect of mutated BAP1 is in line with the tumor suppressive function of intact BAP1 as a deubiquitylase required for efficient assembly of the homologous recombination (HR) factors BRCA1 and RAD51 after DNA double-strand breaks (DSBs)." (PMID 25593912, 2014). "BCP constitute a tumor subgroup associated with BRCA1 mutations." (PMID 24987308, 2014). "The data indicated that BRCA1 methylation was significantly associated with tumor localization." (PMID 24944674, 2014). "For example PARP inhibitors were demonstrated to be synthetic lethal in vitro with mutations in the tumor suppressors BRCA1 and BRCA2 and clinical testing has established the same genetic dependence on tumor sensitivity to the PARP inhibitor olaparib in patients." (PMID 25520658, 2014). "Therefore, we suspect that although MMR pathway is compensatorily activated in response to DSB-repair deficiency, BRCA1 tumours exhibit a weaker MMR pathway compared to BRCA2 tumours because of the direct involvement of BRCA1 in the MMR pathway." (PMID 25521701, 2014). "The deletion of the checkpoint kinase Chk2 in any murine backgrounds with defects in the G2/M checkpoint, including Chk1 heterozygotes, and particular Mre11 complex or BRCA1 alleles, results in tumor predisposition, indicating that the G2/M transition is important for tumor suppression." (PMID 23532176, 2013). "To assess the impact of BRCA1 germline mutations on protein localization, we retrospectively tested 16 of the tumor specimens to determine whether they contained the common Ashkenazi Jewish founder mutations in BRCA1 (185delAG, 5382insC), and BRCA2 (6174delT)." (PMID 23855721, 2013). "However, further studies are needed to fully appreciate the molecular mechanisms underlying the role of BRCA1 as a tumour suppressor." (PMID 23805307, 2013). "Thus it would be beneficial if the tumor cells already harbored DNA repair defects such as the case with BRCA1/2 mutations." (PMID 24289880, 2013). "The ability of the model to mimic clinical rates of tumor ER-status so closely, particularly with regard to a mutation in a single gene (BRCA1) demonstrates the potential benefit and utility of model-aided hypothesis generation and evaluation." (PMID 23704974, 2013). "Our preliminary results suggest low tumor Nmut may identify BRCA-associated primary tumors in which the original deficiency of BRCA1 and BRCA2 pathways, including impaired DNA repair, is compensated for by alternative pathways." (PMID 24265793, 2013). "Finally, analysis of both tumor subtype and FH(+) revealed that 83% (5/6) and 80% (4/5) of patients with FH(+) diagnosed with HR(−) or TN tumors carried a BRCA1 mutation, respectively." (PMID 23469205, 2013). "These considerations suggest that BRCA1 exerts another function(s), perhaps endocrine-related, that collaborates with its role in maintenance of genomic integrity to explain why BRCA1-mutations lead to a specific set of tumor types." (PMID 23802008, 2013). "Loss of BRCA1 protein expression has been recently identified in 38.9% of MMe tissue samples with the highest percentage of BRCA1 immuno-negativity observed in the sarcomatoid MPM tumours." (PMID 23301673, 2013). "We tested 16 of the tumor specimens to determine whether they contained the common Ashkenazi Jewish founder mutations in BRCA1 (185delAG, 5382insC), and BRCA2 (6174delT)." (PMID 23855721, 2013). "Interestingly, the clustering based on gene expression of the 49 tumor samples grouped 93% of the BRCA1/2-negative tumors discriminating from 100% of BRCA1/2-associated tumors." (PMID 23469205, 2013). "It has been suggested that HDR is the major tumor suppressor function for both BRCA1 and BRCA2, since a deficiency in HDR leads to increased levels of NHEJ and single-strand annealing (SSA), both of which are error-prone processes that lead to genomic instability." (PMID 23802008, 2013).
tumor (continued). "BRCA1 follows the classic pattern of a highly penetrant Knudsen-type tumor suppressor gene in which one allele is inactivated through a germ-line mutation and the other is mutated or deleted within the tumor." (PMID 23802008, 2013). "Interestingly, BRCA1 gene generates several splice variants that play an important role in tumor development." (PMID 24082883, 2013). "Therefore, the effect of tumor Nmut on treatment response and outcome was chiefly confined to those tumors with either germline or somatic mutations in BRCA1 or BRCA2." (PMID 24265793, 2013). "The relationship between BRCA1 mutation and methylation has been examined based on the hypothesis that a sporadic tumor with BRCA1 methylation should be similar to a tumor with BRCA1 mutation, if BRCA1 methylation causes tumorigenesis." (PMID 22735547, 2012). "Brca1 mutation shifted the tumor phenotype (p = 0.0529, Fisher's exact)." (PMID 23173005, 2012). "BRCA1 associates with multiple repair proteins and cell cycle regulators and such a capability to form multiple protein complexes contributes to its role in maintaining chromosome stability and tumor suppression." (PMID 22369660, 2012). "Appropriate studies in BRCA1/2-associated tumor models, therefore, would be of interest." (PMID 22984553, 2012). "The fact that AMPK like BRCA1, also inactivates ACCA suggests a mechanism by which MET might substitute for loss of BRCA1 tumor suppressive function." (PMID 26097796, 2012). "The hereditary breast cancer associated gene product, BRCA1 is an essential tumor suppressor." (PMID 22792074, 2012). "Brca1 mutation not only accelerated tumor development but also shifted the tumor spectrum." (PMID 23173005, 2012). "In contrast, a subset of genes including tumor suppressors, such as BRCA1, BARD1 and BLM, were highly deregulated by loss of Spt6 but were only modestly affected or unaffected by loss of PAAF1, even though Spt6 level in these cells was significantly diminished." (PMID 22316138, 2012). "BRCA1 mutated tumours are often triple-negative, and the treatment with PARP inhibitors might be promising in at least some TNBC patients." (PMID 23110154, 2012). "Indeed, the mTOR inhibitor Palomid 529, significantly suppressed BRCA1-deficient tumor growth in mice through inhibition of both AKT and mTOR signaling." (PMID 26097796, 2012). "It is conceivable, therefore, that secondary or reversion mutations of the BRCA1/2 genes, through multiple complex mechanisms, may favor DNA repair by HR and increase tumor cell survival and so trigger resistance to these compounds." (PMID 22481932, 2012). "In gene expression studies, BRCA1-associated tumours are often classified as basal subtype tumours." (PMID 22053997, 2011). "Here, we used an isogenic Brca1 murine mammary epithelial cell (MMEC) model to examine the specific effect of loss of Brca1 on cellular sensitivity to various chemotherapeutic agents in a manner beyond that achievable in less well-characterized human tumor cell lines." (PMID 21771338, 2011). "It is currently unclear whether these polymorphisms are associated with different tumour characteristics within BRCA1 and BRCA2 mutation carriers." (PMID 22053997, 2011). "We assumed that tumours with a BRCA1-like profile could have BRCA1 pathway inactivation due to other causes than a mutation." (PMID 22032731, 2011). "Contribution of Brca1 heterozygosity to tumor susceptibility has been reported." (PMID 21849032, 2011). "We have hypothesized that these tumours harbour a homologous recombination deficiency and thus would be very sensitive to DSB-inducing chemotherapy, similar to tumours arising in BRCA1-mutation carriers." (PMID 22032731, 2011).
tumor (continued). "In total, 18 (12%), 18 (19%) and 16 (43%) BRCA1 mutations were identified in the population-based groups selected on the basis of family history only (n = 150), the group selected on the basis of tumour morphology only (n = 96) and meeting both criteria (n = 37), respectively." (PMID 21281505, 2011). "Interestingly, one tumour which was classified as Sporadic-like by both MLPA and aCGH was hormone receptor positive, whereas all other BRCA1-mutated tumours were triple-negative." (PMID 22032731, 2011). "Preclinical findings indicated that restoration of normal function of BRCA1, in a disease where its loss has been shown to contribute to both its development and progression, could have the therapeutic potential to inhibit tumor growth." (PMID 20182637, 2010). "For example, if the tumour is TN, the probability of carrying a BRCA1 mutation is increased." (PMID 20482762, 2010). "However, the DNA samples used to acquire aCGH profiles for the BLBC and the BRCA1-mutated tumor groups were isolated from fresh frozen tissue and FFPE material respectively, resulting in differences in log2-ratio distribution of the aCGH profiles." (PMID 21118481, 2010). "However, none of these regions have been confirmed in large number of patients and in studies of independent collections of families, and more extensive studies are necessary to find alterations specific to BRCA1/2-mutated tumours." (PMID 20877358, 2010). "Thus, attention has recently focused on taking advantage of the inherent weakness of BRCA1-deficient tumor cells, namely, the inability to effectively repair DNA damage." (PMID 20182637, 2010). "Whether the BRCA1 promoter methylation found in the tumor DNA of the one patient in our series is indicative of loss of wt BRCA1 function is uncertain and its clinical significance is unclear." (PMID 21080930, 2010). "Tumours from BRCA1 and BRCA2 mutation carriers display distinctive pathological features that could be used to better discriminate between BRCA1 mutation carriers, BRCA2 mutation carriers and noncarriers." (PMID 20482762, 2010). "Therefore, the availability of inexpensive expression markers for BRCA1 mutations based on tumor samples would significantly improve the clinical management of these women, and contribute to more efficient prevention within their families." (PMID 19695104, 2009). "The mechanism of this acceleration in tumor initiation and/or progression is unknown, although loss of Brca1 function is associated with genomic instability." (PMID 20046869, 2009). "In the present series, four of the five triple negative tumours (80%) harboured BRCA1 mutations." (PMID 19818148, 2009). "These mouse tumour data raise the question whether platinum resistance can occur at all in BRCA1-deficient tumours that are completely defective in homology-directed DNA repair." (PMID 19904273, 2009). "Mouse models carrying ubiquitin ligase-deficient Brca1 alleles should reveal whether this activity is also dispensable for the tumour suppressor activity of BRCA1." (PMID 19904273, 2009). "This has suggested that underlying BRCA1 abnormalities could promote sporadic basal-like tumour development." (PMID 19589159, 2009). "Importantly, our results show that sporadic tumours with epigenetic silencing of the BRCA1 gene develop similar patterns of genomic alterations as tumours derived from BRCA1 germline mutation carriers." (PMID 19589159, 2009). "This seems to be important as it may explain the protective effect of tamoxifen in the prevention of contralateral tumor development in BRCA1 mutation carriers." (PMID 18405391, 2008). "However, cell lines offer a robust material for understanding tumor biology and response to therapies driven by BRCA1 deficiency." (PMID 18394172, 2008).
tumor (continued). "In particular, expression of CK-5/6 and CK-5/14 has been associated with BRCA1 tumours." (PMID 18275599, 2008). "Of particular importance might be SNPs identified in studies of basal tumor subtypes since they are often clinically aggressive and difficult to treat effectively, and have been associated with germline mutations in BRCA1." (PMID 18437204, 2008). "In that case, IHC staining of PTEN may be a rapid way of identifying tumours most likely to carry BRCA1 mutations." (PMID 18628764, 2008). "Furthermore, tumours with BRCA1 methylation appear to have similar global gene expression profiles to BRCA1 mutated tumours and similar genomic copy number profiles." (PMID 18269736, 2008). "In addition to the CKs, it has been clear for some time that BRCA1-associated tumours have distinct pathological features when compared with sporadic cancers." (PMID 18275599, 2008). "The potential protective effect of pubertal genistein exposure may be linked to an upregulation of Brca1: we noted that this tumour suppressor is upregulated in the mammary glands of rats exposed daily to 50 μg genistein or 10 μg E2 during prepuberty." (PMID 18392054, 2008). "Evidence that genetic factors can also influence tumor type is provided by the fact that carriers of highly penetrant mutations in BRCA1 are more likely to be diagnosed with basal breast tumors which are estrogen receptor (ER) negative, progesterone receptor (PR) negative and HER2 negative." (PMID 18437204, 2008). "Similarly, transplantation of a Brca1 tumor for 2 subsequent passages preserved the molecular features associated with the tumor of origin." (PMID 18394172, 2008). "Our previous analysis of tumour immunohistochemical features of UV carriers suggested disparate results for two tumours from G1738R carriers, a result we confirm here with more detailed immunohistochemical analysis of basal markers of the BRCA1 mutation phenotype." (PMID 18036263, 2007). "Our results suggest that the addition of tumour immunohistochemical expression can add value to the classification of likely causal BRCA1 variants using multifactorial likelihood analysis and that functional assays are a useful adjunct to multifactorial analysis." (PMID 18036263, 2007). "This lends support to the idea that epigenetic silencing of the BRCA1 gene might channel tumour progression, akin to an underlying BRCA1 germline mutation resulting in a BRCA-like phenotype." (PMID 16846527, 2006). "This raises the possibility that the initial stages of tumour formation in BRCA1 and BRCA2 mutation carriers are hormone dependent, in which case early endocrine therapy might be an effective prevention strategy." (PMID 16538216, 2006). "However, Matros and colleagues, looking at gene expression profiles, found a high frequency of BRCA1 promoter methylation among high-grade ER positive tumours, suggesting a more complex phenotype association." (PMID 16846527, 2006). "ER negativity has previously been highlighted to be linked to BRCA1 tumours." (PMID 15642173, 2005). "Aberrant overexpression of such potential ovarian survival/growth regulators on the X chromosome through a mechanism involving the loss of BRCA1 may be involved in ovarian carcinogenesis and/or tumor progression." (PMID 15383145, 2004). "Thus, a prevalence of 2.3–18.5% of occult tumours in BRCA1 or BRCA2 germline mutation carriers has been found." (PMID 15083174, 2004). "Mitotic and apoptotic indexes were higher in Brca1 -associated tumours than in controls." (PMID 11044356, 2000).